ALK (ALK receptor tyrosine kinase)
Diseases named in the same sentence as ALK in open-access papers (continued):
Sharing a sentence is not in itself a finding about the gene and the disease.
squamous cell carcinoma (continued). "Due to the very low rate of patients with squamous cell carcinoma enrolled in clinical trials, the efficacy of ALK inhibitors in patients with ALK-rearranged squamous cell carcinoma in the lung remains unclear." (PMID 34324792, 2021). "It suggested that the ALK alternative in squamous cell carcinoma might to be more complicated than that in adenocarcinoma." (PMID 32727606, 2020). "Therefore, ALK status should be separately described for adenocarcinoma and squamous cell carcinoma." (PMID 32727606, 2020). "Further research is needed to identify whether IHC and/or FISH are the most appropriate techniques for determining the ALK status of patients with squamous cell carcinoma." (PMID 31144459, 2019). "Regarding the NSCLC patients, 6 of them presented with adenocarcinoma (only one with an EGFR mutation and no one with ALK/ROS mutations) and 4 of them with squamous cell carcinoma." (PMID 29874299, 2018). "This suggests that a test for ALK rearrangement should be performed in patients with classical morphologic patterns, mixed squamous and adenocarcinoma patterns as well as in patients with squamous carcinoma in case of a wrong therapeutic decision." (PMID 26253541, 2015). "Interestingly, in our study, we also detected ALK rearrangements in a case of squamous cell carcinoma." (PMID 26253541, 2015). "Importantly, ALK expression was broadly positive, including the areas with squamous cell carcinoma." (PMID 38829559, 2024). "Similarly to the uncertain clinical efficacy of EGFR-tyrosine kinase inhibitor in squamous cell carcinoma, it is also controversy whether ALK rearrangement squamous cell carcinoma patients could benefit from ALK inhibitor." (PMID 32727606, 2020). "Therefore, further studies are needed to examine whether IHC and/or FISH are the most appropriate techniques for determining the ALK status, especially for patients with squamous cell carcinoma." (PMID 31144459, 2019). "Interestingly, one ofthe ALK-positive tumors had a confirmed squamous cell carcinoma." (PMID 30422746, 2018). "Notably, using FISH we found ALK rearrangements in squamous cell carcinomas (2 of 13 cases, 15 %), a clinically relevant finding that deserves specific attention, as 15 % of positive cases would not have been identified if the analysis had been focused on non-squamous cancers only." (PMID 27495736, 2016). "Such are the alterations in BRAF, epidermal growth factor receptor (EGFR) gene, anaplastic lymphoma kinase (ALK) gene, Kirsten Rat Sarcoma virus (KRAS), repressor of silencing 1 (ROS-1) and PD-L1 for squamous cell carcinoma." (PMID 41153394, 2025). "Partial genomic profiling (PCR EGFR and/or FISH/IHC ALK and/or ROS1) was obtained in an additional 23 cases (24%), seven of which were squamous cell carcinomas where EGFR status alone was considered sufficient for treatment decision." (PMID 35108331, 2022). "They recommend systematic biomarker/molecular testing including PDL1, EGFR, ALK, ROS1, and BRAF for all non-squamous cell carcinomas." (PMID 33704175, 2020). "In summary, the present study demonstrated that patients with squamous cell carcinoma should also be routinely tested to determine their EGFR and ALK gene statuses." (PMID 31144459, 2019). "Overall, EGFR/ALK profiling was significantly more often unfeasible in squamous cell carcinoma (17.5%, or 28 of 160 patients) than in non-squamous cell carcinoma (10.4%, or 60 out of 578 patients)." (PMID 39083479, 2024). "AlK-independent resistance includes bypass activation, such as MET and RAF pathway activation or phenotypic transformation, which can be transformed into SCLC and squamous cell carcinoma." (PMID 38961982, 2024). "All ALK- and ROS1-positive cases were found in adenocarcinoma patients, and no ALK or ROS1 fusions were detected in patients with squamous cell carcinoma." (PMID 39685930, 2024).
squamous cell carcinoma (continued). "Diagnostic workup led to diagnosis of T4N3M1b squamous cell carcinoma (SCC), epidermal growth factor receptor (EGFR) and anaplastic lymphoma kinase (ALK) mutations negative." (PMID 34275518, 2021). "The patient was treated with the ALK-TKI alectinib as first-line regimen and achieved a dramatic response without severe adverse events, demonstrating alectinib as a therapeutic option for patients with ALK-positive squamous cell carcinoma." (PMID 34324792, 2021). "All patients with adenocarcinoma underwent genetic testing for EGFR/ALK abnormalities, although this was not routinely performed for squamous cell carcinoma." (PMID 32134200, 2020). "Platinum-based chemotherapy was the most common first-line therapy (non-squamous cell carcinoma [NSQ]: 72.9%; squamous cell carcinoma [SQ] 87.3%, 55/63; patients with EGFR/ALK mutations/rearrangements primarily received tyrosine kinase inhibitors)." (PMID 32912174, 2020). "His third and most recent tumor biopsy specimen collected from his left lung pathologically showed a minute focus of squamous cell carcinoma that was negative for ALK rearrangement by FISH." (PMID 32674491, 2020). "Second, to the best of our knowledge, ALK fusion and EGFR L858R mutations in separate squamous cell carcinoma and adenocarcinoma diagnosed at the same time has not been reported." (PMID 32727606, 2020). "It was very apparent in Case 4 with the adenosquamous carcinoma, where ALK immunostaining occurred in the adenocarcinoma component but not in the squamous carcinoma component." (PMID 23341890, 2013). "Alterations in ALK and FGFR3, present in the RTK/RAS/MAPK signaling pathway, have been reported in cutaneous squamous cell carcinomas; in particular, alterations in ALK have been described as drivers of metastases in squamous cell carcinomas to the lymph nodes." (PMID 39273494, 2024). "The indirect cost per capita was $1670 in non-squamous carcinoma pathological type, $1709 in metastatic clinical stage, $2404 in disease progression, $2080 in immunotherapy, and $1491 in the subgroup with no EGFR mutation and ALK rearrangement." (PMID 36056953, 2023). "The availability of specific inhibitors of ROS1 and their clinical benefit should lead to simultaneous testing of ROS1 rearrangement with other recurrent biomarkers in NSCLC (e.g EGFR and ALK) in all advanced stage never/light smokers with squamous cell carcinoma and non-squamous NSCLC." (PMID 35303812, 2022). "It is of interest to highlight that for non-adenocarcinoma lung tumors, notably for squamous cell carcinoma, but also for other rare histological subtypes such as pulmonary lymphoepithelioma-like carcinoma, the detection of an ALK rearrangement is not mandatory with tissue biopsies." (PMID 33467720, 2021). "However, ALK rearrangement was detected with a frequency of lower than 1% in squamous cell carcinoma, thus was not routinely received molecular testing." (PMID 32727606, 2020). "In stage IV, molecular profiling (gene testing for EGFR, ALK, ROS1 and BRAF) was performed in 94.3% of patients with adenocarcinoma, non-specific carcinoma, or nonsmoking squamous cell carcinoma." (PMID 39147937, 2025). "The absence of ALK and ROS1 rearrangements in squamous cell carcinoma suggests a lesser role for these fusions in that subtype." (PMID 40502411, 2025). "All patients with squamous cell carcinoma were smokers, and the majority of non-smokers were among patients with EGFR and ALK genes abnormalities." (PMID 28969070, 2017). "Interestingly, our ALK immunostaining results indicated that not all tumor cells were ALK-positive staining at the primary sites, especially in adenosquamous carcinoma, in contrast to other studies reporting that the squamous carcinoma component stains positive." (PMID 23341890, 2013). "The high proportion of squamous cell carcinomas in patients who were not tested may be partly due to the rare detection of common oncogenic drivers such as EGFR and ALK." (PMID 39494523, 2024).
colorectal cancer (76 papers, 2013 to 2025). A primary or metastatic malignant neoplasm that affects the colon or rectum. "The ALK fusion-positive cohort included 8 distinct tumor/histological subtypes, the most common of which were colorectal cancer (n = 9; 40.9%), sarcoma (n = 3; 13.6%), and prostate cancer (n = 3; 13.6%)." (PMID 40338218, 2025). "We observed potent and sustained anti-tumor activity with CDX0239-PBD in surface ALK-expressing colorectal carcinoma xenograft models." (PMID 40813394, 2025). "In this study, we detected an ALK fusion with LRRFIP2 as the 5′partner in a case of colorectal cancer." (PMID 39906487, 2024). "Anaplastic lymphoma kinase (ALK) fusion-positive colorectal cancer (CRC) is a rare and chemotherapy-refractory subtype that lacks established and effective treatment strategies." (PMID 38740834, 2024). "All these kinases displayed mutations in more than 6% of CDX2-suppressed colorectal cancers in the TCGA cohort, and some receptor tyrosine kinases, including EGFR, ERBB3, ERBB4, RET, ROS1, and ALK, showed even higher mutation rates in these cancers." (PMID 39452477, 2024). "Another example is the tandem duplication resulting in the C2orf44–ALK fusion, which occurs within chromosome 2 in colorectal cancer, leading to the overexpression of ALK kinase." (PMID 38292185, 2024). "At the time of analysis, the ORR was 50% with one complete response in the leiomyosarcoma patient and partial response in one colorectal cancer patient, again showing that tumors harboring ALK fusions/rearrangement are responsive to ALK inhibitors." (PMID 37773318, 2023). "STRN represented the second most common ALK fusion partner, and were detected in two cases of colorectal cancer and one case of hepatobiliary cancer." (PMID 36369474, 2022). "The observation that ALK is relevant in a small percentage of CRC patient is in agreement with previous reports generated on unselected colorectal cancers specimens." (PMID 35351152, 2022). "To investigate ALK involvement in colorectal cancer, we started from the analysis of a dataset of CRC patients, stratified for consensus molecular subtypes: CMS1, CMS2, CMS3 and CMS4." (PMID 35351152, 2022). "Of note, the involvement of the ALK full-length receptor and its autocrine activation in colorectal cancer has so far been poorly investigated." (PMID 35351152, 2022). "In this study, we found an ALK-independent anti-cancer mechanism of brigatinib in colorectal cancer (CRC)." (PMID 31410188, 2019). "ALK rearrangement has also been identified in 0.4% to 2.5% of colorectal carcinoma (CRC) by exon array profiling, fluorescence in situ hybridization (FISH), and next generation sequencing (NGS) assays performed on archival tumor specimens." (PMID 26172300, 2015). "Moreover, a tandem duplication that leads to C2orf44–ALK fusion occurs in-frame on chromosome 2 in colorectal cancer, resulting in overexpression of the ALK kinase." (PMID 33557176, 2021). "In addition to NSCLC, the ALK fusion gene is also present in colorectal cancer." (PMID 40114680, 2025). "ALK surface expression compared to IgG control was moderate in fusion-positive rhabdomyosarcoma xenograft model RH-41 (geometric mean 7.02x IgG control), and moderate in colorectal carcinoma xenograft models SW-48 (geometric mean 9.76x IgG control) and HCT-116 (geometric mean 5.59x IgG control)." (PMID 40813394, 2025). "Anaplastic lymphoma kinase (ALK) rearrangement has been detected in colorectal carcinoma (CRC) using advanced molecular diagnostics tests including exon scanning, fluorescence in situ hybridization (FISH), and next generation sequencing (NGS)." (PMID 26172300, 2015). "The overall prevalence of RTK fusions in colorectal cancers was 1.0%, with the top frequent fusion genes being RET (0.34%), ALK (0.19%), and NTRK1 (0.10%)." (PMID 36369474, 2022).
colorectal cancer (continued). "In automated immunohistochemistry assay-positive colorectal cancer (CRC) cases, target gene enrichment and sequencing showed that Anaplastic lymphoma kinase (ALK) was fused with a new partner, SPTBN1." (PMID 33390831, 2021). "The SPTBN1-ALK fusion gene was formed by the fusion of exon 7 of the SPTBN1 gene with exon 20 of the ALK gene, which was first identified in colorectal cancer." (PMID 30445769, 2018). "Since copy number gain has been recently associated with poor prognosis in several tumors like RMS, RCC and colorectal cancer (CRC), FISH analysis to assess the impact of copy number variations of ALK in our cohort was performed." (PMID 25083769, 2014). "We evaluated the outcome of 68 patients with advanced colorectal cancer and RAS, BRAF and PI3KCA status according to ALK gene status (disomic vs. gain of ALK gene copy number – defined as mean of 3 to 5 fusion signals in ≥10% of cells)." (PMID 24691006, 2014). "Several reports of MET amplification–mediated resistance to targeted therapies have emerged thereafter, including to anaplastic lymphoma kinase (ALK) inhibitors in ALK-rearranged NSCLC, cetuximab in colorectal cancers, and antiangiogenic therapies in glioblastoma." (PMID 34516823, 2021). "The availability of NGS facilitates a therapeutic genomic paradigm to classify CRC based on actionable genomic biomarkers such as RET, ALK, NTRK, ROS and ERBB2, which may facilitate the clinical trial development of a Colorectal Cancer Genomic Protocol." (PMID 26078337, 2015). "However, ALK CNG has been related to a higher rate of metastatic disease and poor survival in rhabdomyosarcoma and colorectal carcinomas." (PMID 25803816, 2015). "Notably, evidence for a possible involvement of ALK in colorectal cancer has already been suggested, mostly arguing for a cross-talk with EGFR and revealing the presence of tumors harboring both tyrosine kinase receptors alteration or ALK gene amplification as a poor prognostic factor." (PMID 35351152, 2022). "Less frequent mutations were seen in genes that are typically considered “druggable” but not seen previously in colorectal cancer including KIT, ERBB2 and ALK." (PMID 33632293, 2021).
peripheral T-cell lymphoma (72 papers, 2006 to 2026). "ALCLs of all types represent approximately 10–15% of Peripheral T-Cell Lymphomas (PTCLs), distributed between ALK+ ALCL (5–7%) and ALK- ALCL (4–8%)." (PMID 40565334, 2025). "In peripheral T-cell lymphomas, ALK rearrangements with NPM1 and other genetic partners are the most common." (PMID 34944796, 2021). "ALK-positive ALCL is the most curable of the peripheral T-cell lymphomas." (PMID 37655119, 2023). "The prognosis of peripheral T-cell lymphoma patients is significantly poor, and high intratumoral galectin-1 expression before treatment was associated with adverse outcomes in a cohort of patients with CD30+ and ALK− peripheral T-cell lymphoma." (PMID 35677161, 2022). "Among these entities, peripheral T-cell lymphoma, not otherwise specified (PTCL, NOS) with CD30 expression can be particularly difficulty to distinguish from ALK- ALCL." (PMID 37388733, 2023). "Anaplastic large-cell lymphoma (ALCL) accounts for 15% of all peripheral T-cell lymphomas globally and can be further divided into subcategories, of which patients with ALK-negative ALCL have dismal prognosis and overall survival." (PMID 40715645, 2025). "ALK-negative ALCLs show morphologic patterns similar to ALK-positive ALCLs, and a small-cell pattern is not recognized due to overlap with other peripheral T-cell lymphomas." (PMID 34791573, 2022). "ALK-negative ALCL should be treated as for PTCL-NOS (peripheral T-cell lymphoma not otherwise specified)." (PMID 30127547, 2018). "The lowest postrelapse survival rates were seen in ALK-negative peripheral T-cell lymphoma." (PMID 40453056, 2024). "Gene expression profiling (GEP) studies have identified distinct molecular subgroups within ALK-negative ALCL and the broader category of peripheral T cell lymphomas (PTCL)." (PMID 41250242, 2025). "Peripheral T-cell lymphomas (PTCL) encompass several subtypes, including PTCL not otherwise specified (NOS), angioimmunoblastic T-cell lymphoma (AITL), ALK-positive anaplastic T-cell lymphoma (ALCL), and ALK-negative ALCL." (PMID 38331801, 2024). "The study also included 11 peripheral T-cell lymphomas [7 cases of PTCL NOS and one case of hepatosplenic T-cell lymphoma, angioimunoblastic T-cell lymphoma, anaplastic large T-cell lymphoma (ALK-negative) and NK/T-cell nasal type lymphoma, respectively]." (PMID 27861596, 2016). "Peripheral T-cell lymphoma project on the other hand highlighted the outcome differences between PTCL, NOS and ALCL, ALK negative in which 5-year FFS (36% versus 20%) and OS (49% versus 32%) were superior in ALCL, ALK negative compared to PTCL, NOS." (PMID 25143841, 2014). "Recent advancements in molecular diagnostics, such as testing for DUSP22 and TP63 rearrangements, could offer valuable insights into ALK-negative ALCL prognosis and aid in distinguishing it from peripheral T-cell lymphoma (PTCL) NOS." (PMID 39610919, 2024). "In North America, the most common PTCL subtypes are peripheral T-cell lymphoma, not otherwise specified (PTCL-NOS) (34%); angioimmunoblastic T-cell lymphoma (AITL) (16%); anaplastic lymphoma kinase (ALK)-negative anaplastic large-cell lymphoma (ALCL) (16%); and ALK-positive ALCL (8%)." (PMID 35743749, 2022). "However, a subset of peripheral T-cell lymphoma, not otherwise specified (PTCL, NOS) displays large-cell morphology with substantial CD30 expression, rendering a precise distinction from ALCL, ALK negative problematic." (PMID 25143841, 2014).